KDM6B (lysine demethylase 6B)
Diseases named in the same sentence as KDM6B in open-access papers (continued):
Sharing a sentence is not in itself a finding about the gene and the disease.
gastric cancer (continued). "Therefore, we investigated whether KDM6B plays a cancer promoting role in gastric cancer cells that depends on the CXCL12/CXCR4 signaling pathway." (PMID 36564369, 2022). "The results of EdU assays showed that both KDM6B knockdown and the addition of the inhibitor GSK-J4 significantly reduce the proliferation of gastric cancer cells." (PMID 36564369, 2022). "We also analyzed the IHC Score of KDM6B and CXCR4 in gastric cancer tissues and found that they were positively correlated, too." (PMID 36564369, 2022). "To explore the biological functions of KDM6B in gastric cancer, we performed WGCNA analysis using the gastric cancer dataset GSE15460." (PMID 36564369, 2022). "We analyzed the mRNA expression levels of KDM6B and CXCR4 in GEPIA’s gastric cancer database and found that they were positively correlated." (PMID 36564369, 2022). "Further studies showed that the knockdown or addition of the KDM6B enzyme activity inhibitor, GSK-J4, can downregulate the expression of CXCR4 in gastric cancer cells." (PMID 36564369, 2022). "To further investigate the specific mechanisms underlying the role of KDM6B in gastric cancer, we performed RNA-Seq on MKN-45 cells with KDM6B knockdown and the negative control (NC) cells." (PMID 36564369, 2022). "We used H. pylori strains (Hp11637 and Hp26695) to infect the gastric cancer cells, AGS and MKN-45, at different time points (2 h, 4 h, 6 h, and 8 h) based on a 100:1 ratio of bacteria to cells, and then collected the cells to detect the expression of KDM6B." (PMID 36564369, 2022).
Hodgkins lymphoma (10 papers, 2012 to 2024). A heterogeneous group of malignant lymphoid neoplasms of B-cell origin characterized histologically by the presence of Hodgkin and Reed-Sternberg (HRS) cells in the vast majority of cases. "Recently, a finding showed an increase of KDM6B in Hodgkin's Lymphoma caused by Epstein-Barr virus (EBV) which indicated that the demethylase in chicken may also be the main contributor to the change of H3K27me3 induced by MDV infection." (PMID 22848633, 2012). "Anderton and collaborators reported the EBV-mediated deregulation of KDM6B and its role in Hodgkin’s lymphoma, however no previous study has assessed the role of KDM2B in the process of EBV-mediated B cells transformation." (PMID 28724958, 2017).
atherosclerosis (9 papers, 2017 to 2025). A disease characterized by the build-up of fatty material and calcium deposition in the arterial wall resulting in partial or complete occlusion of the arterial lumen. "Our study also provided further insight into the regulatory network and the underlying roles of miR‐15b regulating KDM6B via USP7 in atherosclerosis." (PMID 33434305, 2021). "We previously showed that myeloid Kdm6b deficiency in mice results in advanced atherosclerosis." (PMID 33574814, 2020). "Next, through the analysis of single-cell RNA-seq data and coculture experiments, we revealed that Kdm6b-mediated macrophage activation promoted cytotoxic T lymphocyte cytotoxicity following atherosclerosis progression." (PMID 41423554, 2025). "Experimental knockout of Kdm6b in foam cells delays profibrotic gene transcription, suggesting that Kdm6b is closely connected with atherosclerosis progression." (PMID 41423554, 2025). "When KDM6B was inhibited, it reduced inflammation and slowed down atherosclerosis progression in mice." (PMID 41423554, 2025). "The study concludes that targeting KDM6B could be a potential strategy to treat atherosclerosis by reducing inflammation." (PMID 41423554, 2025). "The study explored how KDM6B affects immune cells called macrophages during atherosclerosis." (PMID 41423554, 2025). "Combining previous studies with our results, a regulatory network could be proposed in the antagonizing atherosclerosis progression that depletion of miR‐15b promoted USP7 expression to up‐regulate KDM6B." (PMID 33434305, 2021). "Finally, we utilized macrophage-specific Kdm6b-knockout mice to determine whether Kdm6b facilitates macrophage and cytotoxic T lymphocyte activation and atherosclerosis." (PMID 41423554, 2025). "However, whether KDM6B is manipulated during macrophage activation and whether m6A modification regulates KDM6B expression in macrophages during atherosclerosis development are unknown." (PMID 41423554, 2025). "Our findings revealed that m6A modification plays a pivotal role in the upregulation of Kdm6b in response to IFN-γ stimulation, which is essential for the phosphorylation of Stat1-induced macrophage activation-mediated atherosclerosis development." (PMID 41423554, 2025).
multiple myeloma (9 papers, 2017 to 2024). "Multiple myeloma cells have high levels of KDM6B expression, and when KDM6B was knocked down, the growth of these cells and their survival were limited." (PMID 37218871, 2023). "KDM6B is highly expressed in multiple myeloma cells and when KDM6B was knocked down, growth and survival of these cells was inhibited." (PMID 34220955, 2021). "In addition to the demethylase activity, KDM6B upregulates the expression of the MAPK signaling pathway components including ELK1 and FOS and then mediates the growth and survival of multiple myeloma cells." (PMID 35783266, 2022).
osteosarcoma (9 papers, 2019 to 2025). A usually aggressive malignant bone-forming mesenchymal neoplasm, predominantly affecting adolescents and young adults. "Upregulated KDM6B facilitates tumor metastasis in osteosarcoma through modulating the lactate dehydrogenase expression." (PMID 35783266, 2022). "Overall, these results indicated that KDM6B depletion significantly inhibited the lung metastasis of osteosarcoma cells in vivo." (PMID 33664867, 2021). "We also analyzed the mRNA expression of KDM6A and KDM6B in 20 matched osteosarcoma and peritumoral tissues; the results showed that compared with normal peritumoral tissue, OS tissue expressed higher levels of KDM6A and KDM6B." (PMID 30651137, 2019). "Our results highlighted that histone demethylase KDM6B played an oncogenic role in the progression of osteosarcoma, KDM6B-mediated H3K27me3 demethylation promotes oncogenic LDHA expression, thereby facilitating OS cell migration in vitro and lung metastasis in vivo." (PMID 33664867, 2021).
rheumatoid arthritis (9 papers, 2019 to 2024). A chronic, systemic autoimmune disorder characterized by inflammation in the synovial membranes and articular surfaces. "Several lines of evidence suggest that H3K27 demethylases, particularly KDM6B, play a role in the pathogenesis of rheumatoid arthritis." (PMID 35915507, 2022). "KDM6B upregulation was also reported in macrophages derived from patients with rheumatoid arthritis and its inhibition blocked excessive TNFα production." (PMID 35915507, 2022). "In auto-immune disease like rheumatoid arthritis, KDM6B induces proliferation and migration of fibroblast-like synoviocytes, which are involved in joint destruction and pathologic processes." (PMID 35902563, 2022).
colitis (8 papers, 2021 to 2025). Inflammation of the colon. "Previous research showed that GSKJ4 could impede the inflammatory response by inhibiting KDM6B and augmenting the NLRP3 transcriptional suppression in colitis." (PMID 37974225, 2023).
myelodysplastic syndrome (8 papers, 2018 to 2024). A clonal hematopoietic disorder characterized by dysplasia and ineffective hematopoiesis in one or more of the hematopoietic cell lines. "In patients with myelodysplastic syndromes and chronic myelomonocytic leukemia, overexpression of KDM6B has been reported." (PMID 34716527, 2023). "In addition, the expression of KDM6B is significantly elevated in specimen of multiple myeloma (MM) patients, in the bone marrow (BM) hematopoietic stem and progenitor cells (HSPCs) of patients with myelodysplastic syndrome (MDS) and chronic myelomonocytic leukemia (CMML)." (PMID 29594337, 2018).
pancreatic cancer (8 papers, 2018 to 2024). "Another study showed that a KDM6B insufficiency could promote the progression of pancreatic carcinoma by decreasing C/EBPα expression." (PMID 33414463, 2021). "A study reported that CEBPA could promote the proliferation, invasion and migration of pancreatic cancer cells, and upregulation of CEBPA can be induced by KDM6B knockdown." (PMID 37857015, 2023).
Sepsis (8 papers, 2018 to 2024). Sepsis is defined as life-threatening organ dysfunction caused by a dysregulated host response to infection. "As a member of miR-106b-25 cluster, miR-93-5p had been proved to play a functional role in osteoarthritis by affecting anti-inflammation and associate to the recovery of sepsis related acute kidney injury by targeting to KDM6B." (PMID 38218880, 2024). "In a mouse model of cecal ligation and puncture (CLP)-induced sepsis, exosomal miR-93-5p inhibited lysine-specific demethylase 6B (KDM6B), reducing TNF-α production and acute kidney injury (AKI)." (PMID 38534389, 2024). "Mesenchymal stem cell-derived exosomes miR-27b can inhibit sepsis by suppressing KDM6B and NF-κB signaling pathway." (PMID 38218880, 2024). "MiR-93-5p was reported to be downregulated in LPS-treated HK2 cells, and participated in sepsis-induced AKI via KDM6B/H3K27me3/TNF-α axis." (PMID 33468219, 2021).
diffuse large B-cell lymphoma (7 papers, 2016 to 2023). "KDM6B has been reported to be overexpressed in diffuse large B-cell lymphoma (DLBCL) and is associated with poor survival." (PMID 34220955, 2021).
esophageal squamous cell carcinoma (7 papers, 2019 to 2024). Esophageal squamous cell carcinoma (ESCC) is a type of esophageal carcinoma (EC) that can affect any part of the esophagus, but is usually located in the upper or middle third. "KDM6B promotes the proliferation and migration of esophageal squamous cell carcinoma by increasing the transcriptional activity of CEBPB." (PMID 38710698, 2024). "In esophageal squamous cell carcinoma (ESCC), the RAS/MEK pathway induces KDM6B overexpression, which is associated with disease stage and patient survival." (PMID 39620228, 2024). "Relevantly, radiotherapy resistance of esophageal squamous cell carcinoma, promoted by hypoxia, has been shown to occur through increased expression of KDM3A and KDM6B." (PMID 35625569, 2022).
non-small cell lung carcinoma (7 papers, 2017 to 2022). A group of at least three distinct histological types of lung cancer, including non-small cell squamous cell carcinoma, adenocarcinoma, and large cell carcinoma. "Since EZH2 and KDM6B have been both associated with EMT and aggressiveness in independent cancer models, we first analyzed their expressions in NSCLCs (Non Small Cell Lung Carcinomas)." (PMID 33291363, 2020). "In non-small cell lung cancer patients, KDM6B significantly decreases in the serum and may play a pro-apoptotic role via promoting the nuclear translocation of FOXO1." (PMID 35783266, 2022). "In contrast, KDM6B overexpression induced cell apoptosis in non-small cell lung cancer (NSCLC) via translocation of FOXO1 indicating that the role of KDM6B may be cell type dependent." (PMID 34220955, 2021). "Similarly, the knockdown of KDM6B inhibits cell apoptosis and promotes cell growth by reducing the nuclear translocation of FOXO1 in non-small cell lung cancer cells." (PMID 28947976, 2017).
Obesity (7 papers, 2020 to 2025). Accumulation of substantial excess body fat. "We observed an increase in the expression of genes encoding CCL2, LEP, and the demethylase KDM6B in vWAT of patients with class II to III obesity, compared to the normal weight/overweight group." (PMID 40518865, 2025). "Further efforts should be performed to confirm the potential role of Kdm6b in the obesity." (PMID 33303977, 2021). "Liver-specific deficiency of KDM6B leads to intrinsic defects in β-oxidation, resulting in hepatosteatosis, glucose and insulin intolerance, whereas its overexpression selectively inhibits lipid levels without increasing glucose levels in patients with obesity, hepatosteatosis, and type 2 diabetes." (PMID 35100965, 2022). "We hypothesize that obesity modulates histone H3K27 marks, modified by demethylases (lysine‐specific demethylase 6A and 6B [KDM6A/KDM6B]) and acetylases (CREB–binding protein [CREBBP]/histone acetyltransferase EP300), affecting ASC function." (PMID 40518865, 2025).
helminth infection (6 papers, 2013 to 2021). "In IL-4 stimulated macrophages, KDM6B-mediated H3K27me3 demethylation increases the expression of M2 marker genes 32, and KDM6B is required for M2 polarization during helminth infection." (PMID 34093857, 2021). "Moreover, LPS, IL-4, or helminth infection induces KDM6B, leading to the modulation of macrophage activation 10-12." (PMID 34093857, 2021).
osteoarthritis (6 papers, 2019 to 2025). A noninflammatory degenerative joint disease occurring chiefly in older persons, characterized by degeneration of the articular cartilage, hypertrophy of bone at the margins and changes in the synovial membrane. "Alternatively, the methyltransferase activity of EZH2 could be inhibited to offset the loss of KDM6B-mediated H3K27 demethylation in osteoarthritis." (PMID 35915507, 2022). "Chondrocyte-specific knockout of KDM6B in mice suppressed the expression of chondrocyte anabolic genes and accelerated osteoarthritis development following surgical destabilisation of the medial meniscus (DMM)." (PMID 35915507, 2022). "Factors thought to drive KDM6B upregulation in damaged cartilage in osteoarthritis include IL-1β and TGF-β, both of which were shown to induce KDM6B expression in cultured human articular chondrocytes (HACs)." (PMID 35915507, 2022). "Indeed, in vivo inhibition of KDM6B with GSK-J4 reversed cartilage erosion in DMM-induced murine osteoarthritis." (PMID 35915507, 2022). "Enhancing rather than inhibiting the demethylase activity of KDM6B may, therefore, normalise or augment cartilage production in osteoarthritis, replacing that which was damage or lost." (PMID 35915507, 2022).
renal cell carcinoma (6 papers, 2012 to 2020). "Compared with adjacent normal tissues, KDM6B expression was significantly increased in renal cell carcinoma." (PMID 28947976, 2017). "Emerging evidence has found that histone demethylases (KDMs), the key regulators in histone modifications, such as KDM3A, KDM5C, KDM6A, and KDM6B, can promote renal cell carcinoma (RCC) progression via hypoxia-mediated angiogenesis pathways." (PMID 32092824, 2020). "In the renal cell carcinoma cell line, ACHN, the siRNA-driven knock-down of lncRNA HOTAIR led to decreased levels of both KDM6B and its target SNAIL1, and then decreased invasion and migration capacities of the cells, suggesting that KDM6B was also regulated at the mRNA level." (PMID 34991274, 2018).
systemic sclerosis (6 papers, 2019 to 2024). A chronic disorder, possibly autoimmune, marked by excessive production of collagen which results in hardening and thickening of body tissues. "Furthermore, in an experimental model of systemic scleroderma a predominant role for KDM6B (JMJD3) was revealed in SSc fibroblasts." (PMID 37476157, 2023). "By contrast, thyroid stimulating hormone receptor (TSHR) and lysine demethylase 6B (KDM6B), which are known primary antigens in autoimmune diseases, including Graves' disease and Hashimoto's disease and systemic sclerosis (SS also termed scleroderma) were highly expressed in asymptomatic males." (PMID 34965855, 2021).
autism (5 papers, 2016 to 2022). Persistent deficits in social interaction and communication and interaction as well as a markedly restricted repertoire of activity and interest as well as repetitive patterns of behavior. "In this study, all five patients with KDM6B variants had neurodevelopment problems, including autism, language delay and intellectual disability." (PMID 36671766, 2022). "The LoF variants in this gene and several members of the same family (KDM3A, KDM5B, KDM6B) have recently been associated with autism in a large scale genetic investigation." (PMID 27257017, 2016). "In alignment with this hypothesis, mutations in both H3K27 demethylases, KDM6A and KDM6B, have been associated with autism, linking defects in a H3K27me3-antagonizing mechanism with autism etiology." (PMID 36417527, 2022). "To examine whether the heterozygous Kdm6b-KO mice develop the core autism-like deficit in sociability, we performed a three-chamber test to examine the voluntary exploration of a social vs. a non-social stimulus." (PMID 35711692, 2022). "RFX transcription factors bind to a X-box consensus motif, which was found by the authors in some neuronal specific enhancers and/or promoters of autism risk genes (such as AP2S1, KDM6B, ANK2, NONO, and MYT1L)." (PMID 34768579, 2021).
cardiac hypertrophy (5 papers, 2016 to 2024). "Other lysine demethylases such as UTX/KDM6A, JMJD3/KDM6B, and JMJD2C/KDM4C have important roles in the differentiation of cardiac cells from their regulating progenitors, but their role in cardiac hypertrophy is elusive." (PMID 27722168, 2016).
depression (5 papers, 2018 to 2025). "KDM6B and ARID1B have been demonstrated to be important in the regulation of depression." (PMID 37235790, 2023).
Alzheimer disease (4 papers, 2018 to 2025). A progressive, neurodegenerative disease characterized by loss of function and death of nerve cells in several areas of the brain leading to loss of cognitive function such as memory and language. "KDM6B seems to prevent some neurodegenerative diseases, such as Alzheimer’s disease, but the most documented disease linked to KDM6B and EZH2 dysregulation is cancer." (PMID 34991274, 2018).
clear cell renal cell carcinoma (4 papers, 2018 to 2022). "Others have reported that high KDM6B expression is associated with increased metastasis and invasion of renal clear cell carcinoma." (PMID 31036064, 2019). "In the clear-cell renal cell carcinoma cell line, Caki-2, KDM6B also directly activated SNAI2 transcription to increase mesenchymal marker expression, decreased epithelial protein expression, and increased invasion capacities." (PMID 34991274, 2018). "We also did not observe any prognostic significance of signature 1, which includes KDM6B, in either breast or renal clear cell cancer, which indirectly substantiates findings from two other reports on KDM6B not being a marker of good prognosis." (PMID 31036064, 2019). "In clear cell renal cell carcinomas, KDM6B expression was also higher in tumor tissues compared to normal ones (tissue-based RT-qPCR, Western blotting, and IHC), and overexpression of KDM6B was also linked to increased tumor size, metastasis, and poor prognosis for patients." (PMID 34991274, 2018).
glomerular disease (4 papers, 2019 to 2024). "Inhibiting lysine demethylase 6b (KDM6B) and 6a (KDM6A) led to elevated H3K27me3 levels in podocytes, which mitigated glomerular disease specifically in diabetic nephropathy models (db/db mice) and in mouse models of Adriamycin-induced nephrotoxicity." (PMID 39595187, 2024). "Conversely, pharmacological inhibition of two demethylating enzymes KDM6A (also called UTX) and KDM6B (also called JMJD3), which specifically demethylate H3K27 dimethylation (H3K27me2) and H3K27 trimethylation (H3K27me3), attenuated glomerular disease." (PMID 30948420, 2019).